AK8 (adenylate kinase 8)
Description:
Nucleoside monophosphate (NMP) kinase that catalyzes the reversible transfer of the terminal phosphate group between nucleoside triphosphates and monophosphates. Has highest activity toward AMP, and weaker activity toward dAMP, CMP and dCMP. Also displays broad nucleoside diphosphate kinase activity.
Synonyms: AK 8; C9orf98; FLJ32704
Tractability: PROTAC: ubiquitination databases record sites on it.
Gene: Protein-coding gene on chromosome 9 (132,725,573 to 132,878,777, reverse strand). Ensembl gene ENSG00000165695.
Subcellular location: Cytoplasm, cytosol; Cytoplasm, cytoskeleton, cilium axoneme
Subcellular location (Human Protein Atlas): Flagellar centriole; End piece; Mid piece; Principal piece
Pathways (Reactome):
Metabolism: Interconversion of nucleotide di- and triphosphates
Gene Ontology:
Molecular function: AMP binding; AMP kinase activity; dCMP kinase activity; nucleoside diphosphate kinase activity; protein binding; ATP binding; nucleobase-containing compound kinase activity; phosphotransferase activity, phosphate group as acceptor
Cellular component: 9+2 motile cilium; cytosol; axoneme; cytoplasm; sperm flagellum
Genetic constraint (gnomAD): Loss-of-function variants: 44 observed, 50.52 expected, observed/expected ratio (o/e) 0.87, 90% interval 0.68 to 1.12. The upper end of that interval is the gene's LOEUF score, 1.12, which puts it in group 4 of 6, group 1 being the genes least tolerant of losing a copy. Missense variants: 504 observed, 558.42 expected, observed/expected ratio (o/e) 0.9, 90% interval 0.84 to 0.97. Synonymous variants: 218 observed, 221.58 expected, observed/expected ratio (o/e) 0.98, 90% interval 0.88 to 1.1.
Homologues: Orthologues: chimpanzee AK8 (99% identical), macaque AK8 (97% identical), dog AK8 (82% identical), pig AK8 (80% identical), mouse Ak8 (77% identical), guinea pig AK8 (77% identical), rat Ak8 (77% identical), rabbit AK8 (56% identical), Drosophila melanogaster CG9541 (11% identical), Caenorhabditis elegans F13E6.2 (11% identical). Paralogues in human: AK9 (23% identical), AK7 (16% identical), AK5 (15% identical), AK4 (12% identical), AK4P3 (12% identical), AK3 (11% identical), AK2 (11% identical), CMPK1 (9% identical), AK1 (9% identical).
Diseases named in the same sentence as AK8 in open-access papers:
AK8 is named in the same sentence as 9 diseases in open-access papers, as found by Europe PMC text mining. Sharing a sentence is not in itself a finding about the gene and the disease. The quoted sentences say what the papers report.
Hydrocephalus (3 papers, 2020 to 2023). Hydrocephalus is an active distension of the ventricular system of the brain resulting from inadequate passage of CSF from its point of production within the cerebral ventricles to its point of absorption into the systemic circulation. "AK8 knockout mice developed mild-to-moderate hydrocephalus, which can be caused by defective cilia blocking the flow of cerebrospinal fluid." (PMID 36727109, 2023). "Interestingly, two related adenylate kinases, Ak7 and Ak8, are also highly expressed in sperm and in multiciliated cells, and mutations in the genes that encode these adenylate kinases (AK7 and AK8) cause hydrocephalus." (PMID 38100419, 2023). "Homozygous AK8 mutations lead to mild to moderate communicating hydrocephalus in mice by 3 wk of age, and loss of Ak8 function does not cause male infertility." (PMID 38100419, 2023).
depression (1 paper, 2023). "But we have got only one shared gene (AK8) by comparing differential transcriptomic analysis and GWAS/WGS data for the obesity and depression pair." (PMID 37494308, 2023).
Obesity (1 paper, 2023). Accumulation of substantial excess body fat. "Similarly, one common gene (AK8) found between obesity and mdd pair in both analyses." (PMID 37494308, 2023).
AK8 also shares sentences with these, for which no sentence is quoted: breast carcinoma (2 papers); communicating hydrocephalus (1); congenital hydrocephalus (1); Hypertension (1); lung adenocarcinoma (1); male infertility (1).